IL4 (interleukin 4)
Diseases named in the same sentence as IL4 in open-access papers (continued):
Sharing a sentence is not in itself a finding about the gene and the disease.
osteomyelitis (2 papers, 2021 to 2024). An acute or chronic inflammation of the bone and its structures due to infection with pyogenic bacteria. "They further discovered that the heterozygous genotype (CT) of IL-4 rs2070874 exhibited protective effects compared to the CC and TT genotypes, while the C allele was identified as a risk factor for hematogenous osteomyelitis." (PMID 39301021, 2024). "It has been definitively established that IL-4 and IL-6 play a direct role in bone resorption and the regulation of osteoclast activity in chronic osteomyelitis." (PMID 39301021, 2024). "Recent studies have uncovered a correlation between the development of osteomyelitis and specific SNPs in IL-4 (rs2243248, rs2243250, and rs2070874) as well as SNPs in IL-6 (rs1800795, rs1800796)." (PMID 39301021, 2024).
Osteopenia (2 papers, 2018 to 2019). Osteopenia is a term to define bone density that is not normal but also not as low as osteoporosis. "This genetic model of SSc is characterized by hyperplasia of the sub-cutaneous loose connective tissue with abnormal dermis, osteopenia and deregulation of the interleukin-4 (IL4)/IL4 receptor (IL4R) signaling pathway." (PMID 30619298, 2018).
otitis media (2 papers, 2017 to 2024). Inflammation of the anatomical structures of the middle ear, which is most often caused by an infectious process. "Kadilya established a rat model of otitis media and reported that kukoamine A could alleviate inflammation in rats by reducing the levels of inflammation-related cytokines, such as interleukin-4 (IL-4), interferon-gamma (IFN-γ), and tumor necrosis factor-α (TNF-α), in a dose-dependent manner." (PMID 39473702, 2024).
otitis media with effusion (2 papers, 2025). Otitis media associated with accumulation of fluid in the middle ear. "The analysis of cytokine levels in adults with OME, including IL-2, IL-4, IL-5, IL-10, IL-12, and interferon (IFN)-gamma, reveals distinct patterns associated with otitis media with effusion (OME) and allergic conditions." (PMID 40497981, 2025).
ovarian serous carcinoma (2 papers, 2019 to 2024). "An investigation focusing on ovarian serous carcinoma indicated a positive correlation between B7-H4 expression and TILs, while noting that B7-H4 expression was not inducible by interleukin-4 (IL-4), IL-6, or IL-10." (PMID 39267740, 2024).
ovarian tumor (2 papers, 2015 to 2023). "However, the lower expression of IL-4 in ovarian tumor tissues should be interpreted with caution." (PMID 25999622, 2015). "Both qPCR and ELISA results showed a reduced expression of anti-inflammatory cytokines including IL-4, IL-10 and TGF-β in murine ovarian tumor after DSF treatment." (PMID 37305383, 2023).
papilloma (2 papers, 2013 to 2017). A benign epithelial neoplasm that projects above the surrounding epithelial surface and consists of villous or arborescent outgrowths of fibrovascular stroma. "However, upregulation of IL-4 expression in the skin after TPA application seems less relevant, as IL-4-deficient mice showed the same incidence in papilloma development as IL-4-competent heterozygous littermate controls." (PMID 24403255, 2013). "Neither deficiency in IL-4 nor in IFN-γ enhanced papilloma formation when compared to heterozygous littermate control mice." (PMID 24403255, 2013). "Because we detected an increase in papilloma incidence in IL-4Rα−/− compared to IL-4−/− mice, we reasoned that IL-13 as the second ligand for IL-4Rα might have been responsible for this difference." (PMID 24403255, 2013). "As a possible mechanism, the dominance of Th2-like cytokine (IL-4 and IL-10) responses and decreased secretion of IFN-γ were reported by peripheral blood mononuclear cells (PBMC) exposed to autologous papilloma tissues in patients with RRP." (PMID 28298239, 2017). "We found that IL-4Rα−/− but not IL-4−/− mice have enhanced papilloma formation, suggesting that IL-13 may be involved." (PMID 24403255, 2013). "A second independent experiment comparing IL-4Rα−/−, IL-4−/−, IFN-γ−/−, and wild-type BALB/c mice showed the same result, namely an increased papilloma incidence in IL-4Rα−/− mice (data not shown)." (PMID 24403255, 2013).
polyarthritis (2 papers, 2012 to 2022). "A substantial (p < 0.0001) downregulation in IL-4,-10, and I-κBα expression in the diseased control group (IL-4: 31.27 ± 1.12%, IL-10: 37.09 ± 0.9%, I-κBα: 55.24 ± 1.04%) in comparison to normal group in CFA induced polyarthritis." (PMID 36234860, 2022).
Polypoidal choroidal vasculopathy (2 papers, 2020 to 2023). The presence of aneurysmal 'polypoidal' lesions in the choroidal vasculature. "The results showed that the level of IL-4 was significantly higher in the three clinical subtypes of AMD, for example, typical AMD, polypoidal choroidal vasculopathy (PCV), and retinal angiomatous proliferation (RAP)." (PMID 32366355, 2020).
pregnancy disorder (2 papers, 2018 to 2021). A disorder that is related to pregnancy. "It has been documented that a deficiency of IL-4 cytokine can lead to infertility and various pregnancy disorders in mammals." (PMID 33920608, 2021). "The IL-4 polymorphisms may be implicated in the impaired Th1/Th2 cytokine balance and may influence implantation defects and pregnancy disorders." (PMID 33920608, 2021). "IL-4 is detectable at the feto–maternal interface and a decrease or lack of IL-4 can lead to a series of pregnancy disorders." (PMID 30319610, 2018).
pregnancy hypertension (2 papers, 2021 to 2022). "Animal models show that the absence of IL-4 is sufficient to induce pregnancy hypertension accompanied by excessive inflammation in IL-4-deficient mice." (PMID 36012236, 2022).
pulmonary edema (2 papers, 2021 to 2024). Accumulation of fluid in the lung tissues causing disturbance of the gas exchange that may lead to respiratory failure. "IL-4 and IL-13 have been detected at high concentrations in patients with virus-associated pulmonary edema, further supporting their role in conditions with pulmonary hypersecretion." (PMID 39052685, 2024). "HFMD patients with brainstem encephalitis or pulmonary edema, or a combination of the two conditions, display diverse plasma levels of IL-8 and TNF-α, with IL-8, IP-10, and IL-4 cytokine levels identified as disease progression predictors." (PMID 34069574, 2021).
Q fever (2 papers, 2017 to 2025). A bacterial infection caused by Coxiella burnetii. "It identified five hub genes (IL4, IL6, IL1B, CD28, and AKT1) that may contribute to the progression of Q fever by regulating immune responses." (PMID 41468478, 2025).
radiation fibrosis (2 papers, 2019). "Although most studies have detected the elevatedlevel of TGF-ß associated with radiation fibrosis, somestudies suggest the greater importance of IL-4." (PMID 31210428, 2019).
relapsing-remitting MS (2 papers, 2024 to 2026). "Our study showed that IL-4 concentrations in the cerebrospinal fluid of patients with newly diagnosed relapsing-remitting multiple sclerosis (RRMS) were significantly higher than those of healthy controls." (PMID 39000506, 2024).
renal failure (2 papers, 2015 to 2022). "Some studies have shown that, when IgAN patients have severe renal insufficiency, the T-adjuvant 2 cytokine interleukin-4 (IL-4) is oversecreted, leading to the downregulation of Cosmc mRNA expression." (PMID 36551160, 2022).
Rotavirus infection (2 papers, 2011 to 2022). Infection with any of the rotaviruses. "Later, it was shown that probiotic LAB had a significant influence on IFN-α, TGF-β, IL-4 and IFN-γ serum responses induced by rotavirus infection in gnotobiotic pigs." (PMID 22046952, 2011).
rubella (2 papers, 2011 to 2022). A viral infection caused by the rubella virus. "Among vaccine responders, rubella vaccination induces a marked increase in IL-4 and IL-10 levels." (PMID 35075197, 2022).
secondary progressive MS (2 papers, 2022 to 2024). "An increase in the number of PBMN (peripheral blood mononuclear cells—cytotoxic T cells, helper T cells, NK cells and B cells), which secrete IL-4, has been reported in both the RRMS and secondary progressive MS (SPMS)." (PMID 39456713, 2024).
selenium deficiency (2 papers, 2020 to 2021). A nutritional deficiency disease resulting from inadequate selenium levels in the body, which can lead to impaired function of selenoproteins essential for antioxidant defense and thyroid hormone metabolism. "Selenium deficiency can shift TH1/TH2 balance toward higher level of Th2 phenotype (IL4 cytokine), while this balance can shift toward TH1 phenotype (IL2, INF-γ cytokine production) in cases with selenium supranutrition." (PMID 35005019, 2021). "As IL-10, IL-13, IL-4, and IL-5 are part of Th2 responses, selenium deficiency may have induced more Th2 responses than Th1 responses in the lungs of mice infected with influenza virus." (PMID 33207753, 2020). "Selenium deficiency decreased the mRNA expression of IFN-γ and IL-2, but increased the mRNA expression of IL-10, IL-13, IL-4, and IL-5 in the mediastinal lymph nodes." (PMID 33207753, 2020).
septic peritonitis (2 papers, 2011 to 2018). Septic peritonitis is an inflammatory condition of the peritoneum that occurs secondary to microbial contamination. "A similar phenomenon was described in a model of severe septic peritonitis, in which a very fast release of IL-4 by MCs upon bacterial encounter resulted in the inhibition of bacterial clearance by peritoneal macrophages." (PMID 30555491, 2018). "In addition, this study provides the first evidence that the phenotypic change produced by N. brasiliensis infection in vivo or by conditioning with IL-4 in vitro protects mice from death from K. pneumoniae-mediated septic peritonitis." (PMID 22110673, 2011).
shigellosis (2 papers, 2017 to 2020). Shigellosis is a bacterial infection leading to dysentery and is caused by Shigella, which are small, ubiquitous Gram-negative bacteria belonging to the enterobacteria family. "The p-values were significant (<0.05) for IL-1β, IL-10, IFN-γ and TNF-α, but IL-2 and IL-4 levels were insignificant in shigellosis patients’ sera." (PMID 28767653, 2017). "IL-4, in conjunction with proinflammatory Th1 and Th2 cytokines, are extensively secreted in rectal biopsies from acute and convalescent adult patients with shigellosis that present severe mucosal inflammation." (PMID 33019492, 2020).
sleep disorder (2 papers, 2023). A change from the patient's baseline sleeping pattern, in the hours slept and/or an alteration/dysfunction in the stages of sleep. "Acupuncture was also reported to improve sleep disorders in PTSD insomnia rats by increasing the TNF content of the hypothalamus and decreasing IL4 expression." (PMID 37200784, 2023).
Sm (2 papers, 2018 to 2019). "Furthermore, a recent study showed that IL-33 needs to synergize with two other cytokine alarmins, thymic stromal lymphopoietin (TSLP) and IL-25, to induce IL-4/IL-13-dependent inflammation and fibrosis after Sm infection." (PMID 31200771, 2019). "Thus, the possible mechanism by which Sm infection suppresses these HIV-specific cellular and humoral responses appear to involve the deposition of SmE in the tissues, which stimulates increased production of IL-4 and IL-10 with concomitant polarization of Th2 immune responses." (PMID 30048550, 2018).
small cell lung carcinoma (2 papers, 2023 to 2024). Small cell lung cancer (SCLC) is a highly aggressive malignant neoplasm, accounting for 10-15% of lung cancer cases, characterized byrapid growth, and early metastasis. "Increased IL4 levels found to be associated with better survival in small cell lung cancer patients receiving ipilimumab immunotherapy." (PMID 37007080, 2023).
soft tissue tumors (2 papers, 2012 to 2014). "This study showed that 52.5% of PBMCs in patients with bone and soft tissue tumors were differentiated into DCs by IL-4 and GM-CSF." (PMID 23300824, 2012). "In addition, the combination of interleukin-4 (IL-4)/GM-CSF/ tumor lysates (TL)/TNF-α induced the greatest differentiation and maturation for DCs in patients with bone and soft tissue tumors in contrast with a combination of IL-4/GM-CSF/TL and a combination of IL-4/GM-CSF/OK-432." (PMID 24741604, 2014). "The combination of IL-4/GM-CSF/TL/TNF-α resulted in the greatest differentiation and maturation for DC-based immunotherapy for patients with bone and soft tissue tumors." (PMID 23300824, 2012).
South American trypanosomiasis (2 papers, 2017 to 2021). "The association with IL4 rs2070874 T/C (p = 0.00712 and OR of 0.6151) is the first time this has been observed in HAT although associations with IL4 have been observed in South American trypanosomiasis." (PMID 29077717, 2017).
squamous carcinoma (2 papers, 2002 to 2021). "On the other hand, IL-4 can modestly stimulate the growth of human squamous cell carcinoma of head and neck cell lines." (PMID 11870521, 2002). "However, expression of M1 markers was decreased in patients with adenocarcinoma and squamous carcinoma; serum levels of interleukin 1 beta (IL-1β), interleukin 4 (IL-4), IL-6, and IL-8 were higher in patients with large-cell carcinoma than in healthy controls." (PMID 34834295, 2021).
status epilepticus (2 papers, 2021). Status epilepticus is defined as a continuous seizure lasting more than 30 min, or two or more seizures without full recovery of consciousness between any of them. "An unexpected finding in the present study was that knock-out of the P2X7R was associated with higher release of cytokines post-status epilepticus, including both pro- and anti-inflammatory cytokines (e.g., IL-10, IL-12p70, IL-27/30, IL-4, KC/GRO MIP-1α, MIP-2, TNF-α)." (PMID 34572093, 2021). "The expression levels of microglial pro-inflammatory cytokines (TNF-α and IL-1β) and anti-pro-inflammator cytokines (IL-10 and IL-4) increase in brain after status epilepticus." (PMID 34924959, 2021). "Both microglial pro-inflammatory cytokines (IL-1β and TNF-α) and anti-inflammatory cytokines (IL-4 and IL-10) showed increased expression after pilocarpine-induced status epilepticus, indicating a complex role of microglia in the epileptic brain." (PMID 34924959, 2021).
Strongyloides infection (2 papers, 2006 to 2017). "Type 2 T helper (Th2) cells that stimulate eosinophils, IgE production, mast cells, and goblet cells by producing IL-4, IL-5, IL-9, IL-10 and IL-13, are important in the defense against strongyloides infection." (PMID 16734908, 2006). "However, higher values of conventional Th2 cells (IL-4+, IL-13+ or IL-5+) correlated with increased Th2/1 hybrid cell frequencies co-expressing IFN-γ and the respective Th2 cytokines (p < 0.0001) irrespective of the Strongyloides infection status." (PMID 28676845, 2017).
syphilis (2 papers, 2017 to 2022). A contagious bacterial infection caused by the spirochete Treponema pallidum. "We prospectively recruited all patients with a new diagnosis of syphilis and tested their plasma for IFNα, IFNγ, IL-1β, IL-12p40, IL-12p70, IP-10, MCP-1, MIP-1α, MIP-1β, IL-4, IL-5, IL-6, IL-7, IL-8, IL-10 and IL-17A at baseline pre-treatment and 6 months following therapy." (PMID 28143443, 2017).
tendinopathies (2 papers, 2010 to 2019). "Suppression of STAT-6 signaling may modulate IL-4 and IL-13 responsive genes known to drive fibrosis in the advanced stages of tendon disease." (PMID 30916999, 2019).
Thrombocytosis (2 papers, 2020 to 2022). Increased numbers of platelets in the peripheral blood. "Production of thrombopoietic cytokine in liver and thrombocytosis are caused by interleukin-1 (IL-1), IL-3, IL-4, IL-11, and tumor-derived platelet factor 4 in tumor host tissues." (PMID 35268446, 2022).
thymoma (2 papers, 2015 to 2023). A neoplasm arising from the epithelial cells of the thymus. "These authors identified eight cytokines that were significantly changed among MG patients with thymoma (i.e., IL-4, IL-8, IL-15, eotaxin, macrophage inflammatory protein-1α, macrophage inflammatory protein-1β, VEGF and IL-1b)." (PMID 25889429, 2015).
thymus atrophy (2 papers, 2014 to 2017). Acquired diminution of the size of the thymus associated with wasting as from death and reabsorbtion of cells, diminished cellular proliferation, decreased cellular volume, pressure, ischemia, malnutrition, reduced function or malfunction, or hormonal changes. "After PRRSV HuN4 challenge, the animals showed obvious clinical signs, including lung lesions, severe thymus atrophy and decreased production of IL-4 and higher level of viremia." (PMID 24507659, 2014).
thyroid (2 papers, 2014 to 2019). "Further cytokine analyses have shown that IFN-γ, IL-4 and IL-17, the effector cytokines of Th1, Th2 and Th17 respectively, are expressed in the thyroids of NOD.H-2h4 mice with iodine-induced thyroiditis." (PMID 25050783, 2014). "Ablation of IFN-γ, or IL-17, but not IL-4, in NOD.H2h4 mice demonstrated resistance to both thyroiditis and the generation of anti-thyroglobulin autoantibodies, indicating that both Th1 and Th17 cells are the T-cell subsets critical for the pathogenesis of iodine-induced AIT in these mice." (PMID 25050783, 2014).
tongue cancer (2 papers, 2019 to 2025). A malignant neoplasm affecting the tongue. "In mouse models with tongue cancer, the addition of Lactobacillus fermentum increased the levels of G-CSF, GM-CSF, IgG, IgM, IL-4, IL-12, TNF-alpha, and IFN-gamma." (PMID 41155504, 2025). "In this study, LF-CQPC08 increased the serum levels of IL-4, IL-12, TNF-α, and IFN-γ in mice with induced tongue cancer, thereby regulating the immune system and inhibiting the tongue cancer in the mouse model." (PMID 30861992, 2019). "The serum IL-4, IL-12, TNF-α, and IFN-γ levels of the mice in the normal group were the highest, while the results in the mice with induced tongue cancer in the control group were the opposite." (PMID 30861992, 2019).
tongue SCC (2 papers, 2021 to 2022). "In contrary, IL-4-producing CD4+ T cells was higher in advanced stages and in tongue SCC patients with larger tumor size which are linked to a poor prognosis." (PMID 36376825, 2022).
tonsillitis (2 papers, 2020 to 2024). Inflammation of the tonsillar tissue. "In a recent study conducted on pediatric cases with PFAPA syndrome, it was found that the IL-4 serum level in PFAPA cases was significantly reduced compared with recurrent tonsillitis cases." (PMID 39119144, 2024).
toxic epidermal necrolysis (2 papers, 2006 to 2025). Toxic epidermal necrolysis (TEN) is an acute and severe skin disease with clinical and histological features characterized by the destruction and detachment of the skin epithelium and mucous membranes. "Detectable amounts of IL-4 and IL-10 and ofsoluble IL-2R have been measured in the blister fluid of patientswith toxic epidermal necrolysis, a disease in which the earlyparticipation of activated CD8+ T lymphocytes play animportant role." (PMID 16864900, 2006). "Severe cutaneous adverse reactions, including DRESS, SJS, and toxic epidermal necrolysis (TEN), involve pathogenic mechanisms in which cytotoxic CD8+ T lymphocytes, as well as certain pro-inflammatory eosinophil promoting cytokines (such as IL-4, IL-5, IL-9, IL-13), play a role." (PMID 40869188, 2025).